CCL21 (C-C motif chemokine ligand 21)
Diseases named in the same sentence as CCL21 in open-access papers (continued):
Sharing a sentence is not in itself a finding about the gene and the disease.
tumor (continued). "In a striatal tumor model, VEGF-C overexpression induces meningeal lymphangiogenesis, displaying a synergy effect with anti-PD-1/cytotoxic T-lymphocyte-associated protein 4 (CTLA-4) therapy, which can be abolished by CCL21/CCR7 blockade." (PMID 41511312, 2025). "Because tumor-draining LNs (tdLNs) have been reported to downregulate CCL21 in some mouse model and human studies, we tested whether iLNs responding to subcutaneous MC38 tumors would exhibit increased EBI2 dependency for naive lymphocyte recruitment." (PMID 39708807, 2025). "Innate immune cells, such as mature dendritic cells (mDCs) and M1-like tumor-associated macrophages (TAMs), secrete cytokines, such as IFN-α, IL-12, IL-18, and TNF, along with chemokines like CXCL9, CXCL10, and CCL21, which effectively suppress tumor angiogenesis." (PMID 40322886, 2025). "Notably, there was a significant increase in the expression of the chemokines CCL19 and CCL21 at the tumor site, especially in the M-HIFU-treated group." (PMID 39861713, 2025). "The enhanced anti-tumor effect of the combination of anti-PD-1 antibody and CCL21 in our vivo experiments fully supports this hypothesis." (PMID 38367070, 2024). "However, M057 normalizes tumor vasculature in lung tumors and promotes CCL21-mediated DC migration into tumors." (PMID 38250037, 2024). "When the recruiter CAF_CCL21 is deficient, the loss of the CXCL12-CXCR4 axis recruitment impairs the infiltration of B_CD74 responders, disrupting B cell-mediated antigen presentation and suppressing the anti-tumor effect of CD8+ T cells." (PMID 38505619, 2024). "To test this hypothesis, we first performed ssGSEA based on TCGA-LIHC cohort to determine the relative abundance of immune cells in tumor tissues with different CCL21 expression level." (PMID 38367070, 2024). "This outlines a mechanism of how tumor cells regulate the immune microenvironment through CCL21." (PMID 39456552, 2024). "Moreover, both CCL21 and tumor-triggered pDC activation can be blocked by either CCL21 or CCR7 antibody neutralization." (PMID 39456552, 2024). "Tumor cells expressing CCR7 could interact with CCL21 produced by lymphatic endothelial cells, resulting in lymphatic metastasis of tumor cells." (PMID 39175095, 2024). "Moreover, CXCR4 and CCR7 interact with their respective ligands chemokine (C-X-C motif) ligand 12 (CXCL12) and chemokine (C-X-C motif) ligand 21 (CCL21), enabling tumor cells to have “chemotaxis” and promoting their metastasis to the intended organs." (PMID 38549934, 2024). "Given the features of tumor immune infiltration have been acknowledged as pivotal factors impacting the response to immunotherapy, we hypothesized that CCL21 might potentiate the efficacy of ICIs in HCC." (PMID 38367070, 2024). "In a phase I trial, the safety and specificity of immune responses to tumor antigens were evaluated following in situ vaccination with autologous DCs transduced with an adenoviral vector expressing the CCL21 gene in patients with advanced non-small cell lung carcinoma." (PMID 39588373, 2024). "Blockade of CD93 with monoclonal antibodies against CD93 (anti-CD93) markedly inhibited lung tumor growth by inducing CCL21 secretion from pMCs and preventing tumor angiogenesis, thus showing better efficacy than blocking vascular endothelial growth factor receptor (VEGFR)." (PMID 38250037, 2024). "As a first step, we set forth to verify that the observed reduction in CCL19 and CCL21 in healthy mice was also present in B16F10-Luc tumor-bearing mice treated with the treatment regimens used throughout this study (“TM IR + ICI”, “TM + C-DLN IR + ICI” and “TM + NEO-DLN IR + ICI”)." (PMID 38951172, 2024). "An in vitro study reported an oncolytic adenovirus co-expressing chemokine CCL21 and IL-21 that could selectively replicate in TERTp-positive tumor cells (Ad-CCL21-IL-21 virus) was able to induce direct lysis of tumor cells by cytotoxic T cells." (PMID 38638431, 2024).
tumor (continued). "Salmonella Typhimurium has been used in immunotherapies in murine trials, with significant tumor reduction, resulting from the local expression of bacteria or the expression of immune system-stimulating molecules on tumor cells IL-18, CCL21, LIGHT, or the Fas ligand." (PMID 39594765, 2024). "Tumor-associated fibroblasts at the primary tumor site can secrete lymphangiogenic factors like VEGF-C, COX-2, HIF1 alpha chemokines like CCL21, CXCL12, which affect lymphatic endothelial cell permeability, adhesion molecule expression, migration to form nascent capillaries, and ECM remodeling." (PMID 38473419, 2024). "Besides, TT-EV miR-5193 level was also positively correlated with the CCL21 level and the numbers of CD11c+ DCs, CD4+ T cells and CD8+ T cells in tumor tissues and the CCL21 level and DC number were also positively correlated." (PMID 38250037, 2024). "Knockdown of Ccl21 gene expression also severely attenuates metastatic tumor growth." (PMID 37426658, 2023). "Thus, CCL21 expressed by cancer cells and stromal cells in the tumor microenvironment confers metastatic capacity to cancer cells to the regional LNs." (PMID 37664721, 2023). "Next, we tested whether CCL21 may mediate the activation and the tumor-supportive polarization of microglia/macrophages." (PMID 37314567, 2023). "•The host-derived CCL21-Ser has different effects on tumor growth depending on tumor cell types." (PMID 37664721, 2023). "In addition, CCL21 promotes antitumor immune response by inducing tumor antigen presentation and suppressing the production of immunosuppressive cytokines in human breast cancer cells." (PMID 37664721, 2023). "Besides, inducing tumor cells to overexpress CCL19 or CCL21 by transfection also enhances the functions of DCs and tumor control." (PMID 38008741, 2023). "The expression of CCL21 within the HL microenvironment may affect the organization of tumor and immune cells within the affected lymph nodes, potentially influencing disease progression and specific immune responses." (PMID 37958472, 2023). "Thus, nonclassical monocytes influence CD8+ TEM cell maturation, via the chemokine CCL21, that are responsible for blocking tumor seeding in the lungs." (PMID 37426658, 2023). "With the exception of CCL21, all other genes were upregulated in the tumor group." (PMID 38054797, 2023). "Thus, although the impact of the CCL21/CCR7 signaling on anti-tumor immunity remains controversial, the fact that CCL21 expression can induce an immune response provides a rationale for the use of CCL21 in cancer immunotherapy." (PMID 37664721, 2023). "Therefore, this study assessed the role of endogenous CCL21-Ser in tumor growth and immune cell infiltration in tumor tissues using Ccl21a-KO mice." (PMID 37664721, 2023). "In cancer, CCL21 can have additional functions, including altering the host immune response from immunogenic to tolerogenic by promoting the formation of lymphoid-like stromal components, which then impacts on tumor progression." (PMID 37377898, 2023). "CCL21, CCL22, and CCL24 are genes encoded by C–C motif chemokine ligands, which are components of intercellular communication and essential in the functioning of the tumor microenvironment." (PMID 37537613, 2023). "In addition to this mechanism, tumor cells respond to the chemokine CCL21, which facilitates chemotaxis in CCR7+ expressing cells." (PMID 36158182, 2022). "Therefore, targeting the CCL19/CCL21/CCR7 axis to inhibit lymphatic metastasis but maintaining a robust antitumor immune response has increasingly become a bright spot in tumor immunotherapy." (PMID 35702353, 2022). "VEGF-C mediated potentiation of adoptive T-cell therapy was dependent on CCR7-mediated attraction of naïve T cells to the local TME; this was shown to occur through VEGF-C-induced CCL21 upregulation in tumor lymphatics because CCR7 blockade reversed the potentiating effects of VEGF-C." (PMID 35216243, 2022).
tumor (continued). "In addition, the high expression of CCR7, CCL21 inhibited the function of dendritic cells and hindered the killing effect of T cells on tumor cells." (PMID 35309316, 2022). "Furthermore, the overexpression of VEGF-C was shown to increase lymphatic transport, T cell recruitment through increased levels of CCL21, and T cell activation for a variety of tumor antigens." (PMID 36158182, 2022). "High levels of CCL21 expression, which is often upregulated in invasive cancer cells, induce the formation of stromal-like structures in mouse melanoma tumours that resemble those formed by FRCs in the lymph node." (PMID 35072206, 2022). "Thus, PNAd+ CCL21+ intratumoral vessels contribute to anti-tumor immunity by generating a self-sustaining infiltration of naïve T cells into the tumor mass." (PMID 36189308, 2022). "CCL21 was used in a syngeneic 4T1.2 mouse breast model to attract ILC3s to primary tumors, which then induces tumor stromal cells to secrete CXCL13, and then results in lymphotoxin and activates receptor of NF-κB ligands, which stimulate tumor cell migration and lymphangiogenesis." (PMID 36419156, 2022). "Besides, the tumor volume was significantly larger in the anti-CCL21 treatment group than in the IgG isotype group." (PMID 35301438, 2022). "The transcriptional levels of 5 chemokines (CXCR5, CXCL12, CXCL13, CCL19, and CCL21) that have been reported to be involved in the formation of TLSs were also prominently elevated in both the tumor specimens from mIgG2c-G400R mice and hIgG1-G396R homozygous CRC patients." (PMID 35133976, 2022). "But, the function of CCL21 throughout tumor progression time remains slightly debatable." (PMID 35874608, 2022). "CCL21 is one of the effective chemo-attractant for tumor-penetrating white blood cells." (PMID 35874608, 2022). "CCL21/CCR7 has been gradually recognised as a potential therapeutic target in many tumours." (PMID 35280672, 2022). "Thus, mice were injected with 50,000 4T1-Luc cells, and once the tumour became visible on day 7, they were treated with mut-CCL21 or PBS (i.v.)daily for one week." (PMID 34298676, 2021). "Tumor cells increase VEGF-C expression in response to the CCL21/CCR7 signal." (PMID 34160019, 2021). "Remarkably, stroma in oral squamous cell carcinomas has lymphoid properties characterized by abundant FRCs expressing extracellular matrix components of lymph nodes including tenascin-C and utilizing CCR7/CCL21 signaling for retaining CD11c+ immune cells in the tumor matrix tracks." (PMID 33912190, 2021). "However, lymph node invasion is usually the first step in the metastatic process, where CCR7-expressing tumour cells are attracted to its ligand CCL21 that is abundantly expressed in the lymph nodes." (PMID 34298676, 2021). "These authors could show that both ectopic syngeneic or orthotopic autochthonous tumors are infiltrated by immune cell populations following CCL21 therapy, leading to a potent anti-tumor effect." (PMID 34276690, 2021). "DCs, derived from myeloid cells, can cross-present tumor antigens to T lymphocytes in draining lymph nodes, and studies have shown that DC-AdCCL21 cells modified by the CCL21 gene have resulted in extensive monocyte infiltration and significant reduction in tumor load." (PMID 34777372, 2021). "Since ACKR4 regulates the CCL21 chemokine gradient, we hypothesized that loss of ACKR4 in tumor tissue would increase the CCL21 levels in the tumor microenvironment." (PMID 34638505, 2021). "It is therefore interesting to speculate that modulation of blood flow dynamics and transport of cytokines/chemokines during tumor blood vessel normalization may regulate Ccl21 expression levels in the vascular bed, and thus TLS formation in vivo." (PMID 34122434, 2021). "Indeed, the CCR7/CCL21 axis promotes the growth and metastasis of many tumour types, including melanomas, breast, thyroid, colon, head, and neck cancers." (PMID 34298676, 2021).
tumor (continued). "A possible strategy could be to encapsulate mut-CCL21 in sterically stabilised immunoliposomes, which are guided by antibodies that bind specifically to antigens on the tumour cell surface." (PMID 34298676, 2021). "Finally, we determined that the CCL21 level in the ACKR4 knockdown tumor tissues was significantly higher than in the wild-type and control groups." (PMID 34638505, 2021). "Moreover, the ability of CCL21 to transform the immunogenic host immune response to tolerogenic response has been reported, which ultimately stimulates tumor progression." (PMID 34001131, 2021). "In comparison to the monotherapy that reduced tumor burden without causing tumor eradication, treatment groups receiving CCL21-DC tumor lysate vaccine plus anti-PD-1 led to 80% tumor eradication." (PMID 32570793, 2020). "Interestingly, there are also studies suggesting that whenever tumor cells express CCL21 it has an anti-tumorigenic effect through the inhibition of angiogenesis and increase of leukocyte recruitment, in particular of CD8 + T-cells and DCs." (PMID 32340161, 2020). "Similarly, tumor lysate pulsed CCL21-DC vaccine administered prior to combined therapy led to 90% tumor eradication." (PMID 33167311, 2020). "CCL21-DC peptide vaccine administered prior to combined therapy led to 100% tumor radication." (PMID 33167311, 2020). "Chemokine (C-C Motif) ligand 21 (CCL21) plays an important role in tumor immunity." (PMID 29687228, 2020). "Additionally, CCL21 has been shown to promote the generation of new lymphoid-like structures within the tumor microenvironment, which are characterized by the infiltration of immune-suppressive T-regulatory cells and myeloid-derived suppressor cells." (PMID 32340161, 2020). "In addition, it was confirmed CCL21-FA-UCNPs@mesoporous silica effectively induced T cell migration to tumor cell sites using the Transwell system." (PMID 33240857, 2020). "However, the role of CCL21 during tumor progression remains somewhat controversial, with tumor-suppressive properties also been reported." (PMID 32340161, 2020). "The prognostic value of CCL21 in cancer patients is significant varies according to the tumor type." (PMID 33146700, 2020). "Previous studies have revealed that CCL21 may facilitate infiltration of immune cells into the tumor area, leading to the production of an anti-tumor cell immune response and suppression of tumor growth." (PMID 33146700, 2020). "Additionally, the production of CCL21 by the HEV endothelial cells recruits naïve CCR7+ T cells to tumor sites, which are essential in the generation of anti-tumor immunity." (PMID 32499782, 2020). "The function of CCR7/CCL21 in cancer appears to be controversial; it may play a pro- or anti-tumor function depending on where it is expressed." (PMID 32340161, 2020). "In a stage I clinical trial, DCs were transduced with an adenoviral (Ad) vector expressing the CCL21 gene (Ad-CCL21-DC), which induced systemic tumor antigen-specific immune responses, enhanced tumor CD8+ T cell infiltration, and increased tumor PDL1 expression." (PMID 32746880, 2020). "Interestingly, the swelling of dCLNs was weakened after anti-CCL21 or anti-CCR7 treatment in tumor-bearing mice." (PMID 32094452, 2020). "Analysis of the total thymic cell population suggests insignificant changes in CCL17 (ligand for CCR4) and a modest decrease in CCL19 (ligands for CCR7) at day 25 but a drastic reduction in expression of CCL21 (ligands for CCR7) when comparing thymi harvested from tumor-bearing vs. control mice." (PMID 32582141, 2020). "In this context, administration of HPV16 E7 DNA vaccine adjuvanted with anti-PD-1 and secondary lymphoid-tissue chemokine (CCL21 or SLC) or the toll like receptor agonist and α-Galactosylceramide in tumor-bearing mice models resulted in both tumor regression and tumor growth suppression." (PMID 32973401, 2020). "CCL21 plays important roles in tumor apoptosis, infiltration, metastasis, and angiogenesis." (PMID 29687228, 2020).
tumor (continued). "They developed an in vitro endothelial-tumor cell bilayer model and demonstrated that CCL21-FA-UCNPs@mesoporous silica could selectively target folate receptor (FR)-expressing OVCAR-3 cells." (PMID 33240857, 2020). "In addition, the specific binding of CCL21 to C-C chemokine receptor type 7 (CCR7) expressed on the surface of tumor cells can promote lymph node metastasis of tumor cells." (PMID 33240857, 2020). "CCL21-DC tumor antigen vaccine induced infiltration of T cells that was activated by PD-1 blockade." (PMID 33167311, 2020). "The lower levels of NK cell chemoattractants (CCL27, CCL21) in the tumor microenvironment may participate to the immunosuppressive mechanism of the tumor by limiting cytolytic cell recruitment." (PMID 31105699, 2019). "CCL21 can both regulate biological functions of tumor cells and immune cells." (PMID 31523177, 2019). "CCL21 has also been shown to promote lymphoid-like stromal components and immune escape in melanoma tumors in mice, raising the concept that CCL21-secreting tumors can alter the host immune response from immunogenic to tolerogenic which then impacts on tumor progression." (PMID 31105685, 2019). "In this model, NKp46- ILC3s were recruited thanks to CCL21 produced by 4T1 tumor cells." (PMID 31024531, 2019). "In particular, CCL21, which binds podoplanin with high affinity and is secreted by LECs and tumor cells, could facilitate the access of tumor cells to lymphatic vessels." (PMID 30736372, 2019). "The interaction of tumour cells with lymphatic cells can be promoted by interstitial fluid (resulting from lymphatic drainage) via autologous chemotaxis involving the chemokine CCL-21 and its receptor, CCR-7, expressed by tumour cells." (PMID 30406137, 2018). "Lymph endothelial cells secrete chemokines including chemokine (C-X-C motif) ligand 12 (CXCL12) and chemokine (C-C motif) ligand 21 (CCL21) to recruit tumor cells that express chemokine (C-C motif) receptor 7 (CCR7) and chemokine (C-X-C motif) receptor 4 (CXCR4)." (PMID 29805773, 2018). "Previously, we showed that use of an adenoviral CCL21 gene modified DC-based tumor vaccine could enhance T cell recruitment in vivo." (PMID 29617362, 2018). "One could envision CCL21 being part of post transplant therapy when immune reconstitution is critical for viral clearance and anti-tumor immunity; thus CCL21 could bolster the immune response resulting in decreased morbidity and mortality." (PMID 29617362, 2018). "Most importantly, tumor suppression by T-cells pre-cultured on CCL21 + ICAM1 persisted throughout the 14-day experiment, with almost no increase in tumor size over time, compared to the constantly growing tumors treated with T-cells pre-cultured on uncoated substrates." (PMID 29942308, 2018). "To assess the capacity of CCL21 + ICAM1-stimulated CD8+ T-cells to suppress tumor development in vivo, we treated mice bearing B16-ovalbumin tumors with T-cells that were pre-cultured for 7 days on either uncoated substrates, or on substrate-immobilized CCL21 + ICAM1." (PMID 29942308, 2018). "CCR7+ carcinoma cells, as they are less retained in the primary tumor site, might thus be attracted to CCL21+ sites such as peripheral lymph nodes, where the chemokine is presented on endothelial cells as shown in this work." (PMID 28416768, 2017). "CCL21 expressions were mostly found in cytoplasm of tumor cells." (PMID 27783999, 2017). "CCL21-mediated help of tumor regression was shown to depend on host T and NK cell activity." (PMID 28416768, 2017). "CCL21 has the potential to induce effective anti-tumor immunity and suppress immune tolerance." (PMID 27783999, 2017). "The CCL21 expression levels in the cell lines were significantly lower than the in therapy-naive tumor samples, with a large variation of expression levels between tumor samples compared to cell lines." (PMID 27369431, 2016).